ENSG00000273499
Synonyms: LOC124900333
Gene: Small nucleolar RNA gene on chromosome 12 (108,778,144 to 108,778,271, reverse strand). Ensembl gene ENSG00000273499.
Gene Ontology:
Biological process: RNA processing
Cellular component: nucleolus
Homologues: Paralogues in human: SNORA40B (85% identical), SNORA40 (84% identical), SNORA40C (83% identical).